TMPRSS11F (transmembrane serine protease 11F)
Description:
Probable serine protease.
Synonyms: HATL4; FLJ16046
Tractability: Antibody: UniProt predicts a signal peptide or a membrane-spanning region; its Gene Ontology location is reachable by antibodies, with medium confidence. PROTAC: ubiquitination databases record sites on it.
Gene: Protein-coding gene on chromosome 4 (68,053,198 to 68,129,869, reverse strand). Ensembl gene ENSG00000198092.
Subcellular location: Membrane
Gene Ontology:
Molecular function: serine-type peptidase activity; serine-type endopeptidase activity
Biological process: protein processing; proteolysis
Cellular component: cell surface; plasma membrane; extracellular region; membrane
Genetic constraint (gnomAD): Loss-of-function variants: 34 observed, 45.55 expected, observed/expected ratio (o/e) 0.75, 90% interval 0.57 to 0.99. The upper end of that interval is the gene's LOEUF score, 0.99, which puts it in group 4 of 6, group 1 being the genes least tolerant of losing a copy. Missense variants: 426 observed, 454.88 expected, observed/expected ratio (o/e) 0.94, 90% interval 0.86 to 1.01. Synonymous variants: 140 observed, 147.23 expected, observed/expected ratio (o/e) 0.95, 90% interval 0.83 to 1.09.
Homologues: Orthologues: macaque TMPRSS11F (96% identical), chimpanzee TMPRSS11F (95% identical), rabbit TMPRSS11F (89% identical), rat Tmprss11f (87% identical), mouse Tmprss11f (87% identical), guinea pig TMPRSS11F (84% identical), pig TMPRSS11F (83% identical), zebrafish tmprss15 (26% identical), zebrafish st14b (25% identical), zebrafish st14a (25% identical), Drosophila melanogaster Sb (25% identical), tropical clawed frog tmprss12 (23% identical), and 3 more. Paralogues in human: TMPRSS11E (42% identical), TMPRSS11A (41% identical), TMPRSS11D (39% identical), TMPRSS11B (38% identical), TMPRSS3 (29% identical), HPN (28% identical), ST14 (28% identical), TMPRSS2 (28% identical), TMPRSS6 (27% identical), TMPRSS7 (27% identical), PRSS22 (25% identical), TMPRSS13 (25% identical), and 5 more.
Diseases named in the same sentence as TMPRSS11F in open-access papers:
TMPRSS11F is named in the same sentence as 7 diseases in open-access papers, as found by Europe PMC text mining. Sharing a sentence is not in itself a finding about the gene and the disease. The quoted sentences say what the papers report.
tumor (3 papers, 2019 to 2023). "Among AR-association gained genes, new candidate genes that strongly associated with aggressive tumor traits were sprouty related EVH1 domain containing 3 (SPRED3), transmembrane serine protease 11F (TMPRSS11F) and solute carrier family 1 member 1 (SLC1A1)." (PMID 36809527, 2023). "Conversely, some genes are associated with both tumor status and survival (MUC4 for HNSC, TMPRSS11F, SLC6A18, and DEFB119 for LGG)." (PMID 32625238, 2020).
cancer (2 papers, 2019 to 2020). A tumor composed of atypical neoplastic, often pleomorphic cells that invade other tissues. "In summary, our analysis framework confirmed six well-known cancer-related genes, supplied additional evidence to support four other suspected cancer-related genes, and identified one novel potentially strongly predictive factor, methylation of TMPRSS11F." (PMID 32625238, 2020). "One gene, TMPRSS11F, has not been discussed in the cancer context before, to the best of our knowledge [see also]." (PMID 32625238, 2020).
TMPRSS11F also shares sentences with these, for which no sentence is quoted: acute promyelocytic leukemia (1 paper); leukemia (1); myeloid leukemia (1); prostate carcinoma (1); virus infection (1).